HSD17B8 (hydroxysteroid 17-beta dehydrogenase 8)
Synonyms: HKE6; D6S2245E; RING2; KE6; H2-KE6; SDR30C1; FABG; FABGL; dJ1033B10.9
Tractability: Small molecule: a structure with a bound ligand is known; it has a high-quality binding pocket. Antibody: its Gene Ontology location is reachable by antibodies, with medium confidence. PROTAC: ubiquitination databases record sites on it; its protein half-life has been measured.
Gene: Protein-coding gene on chromosome 6 (33,204,631 to 33,206,831, forward strand). Ensembl gene ENSG00000204228.
Pathways (Reactome):
Metabolism: Fatty acyl-CoA biosynthesis
Gene Ontology:
Molecular function: (3R)-3-hydroxyacyl-CoA dehydrogenase (NAD+) activity; estradiol 17-beta-dehydrogenase [NAD(P)+] activity; NADH binding; protein binding; quinone binding; 17-beta-hydroxysteroid dehydrogenase (NAD+) activity; testosterone dehydrogenase (NAD+) activity
Biological process: estrogen biosynthetic process; fatty acid biosynthetic process; protein heterotetramerization; estrogen metabolic process
Cellular component: mitochondrial matrix; mitochondrion; oxidoreductase complex; endoplasmic reticulum; membrane; mitochondrial envelope; plasma membrane
Genetic constraint (gnomAD): Loss-of-function variants: 23 observed, 31.95 expected, observed/expected ratio (o/e) 0.72, 90% interval 0.52 to 1.02. The upper end of that interval is the gene's LOEUF score, 1.02, which puts it in group 4 of 6, group 1 being the genes least tolerant of losing a copy. Missense variants: 345 observed, 322.5 expected, observed/expected ratio (o/e) 1.07, 90% interval 0.98 to 1.17. Synonymous variants: 137 observed, 127.11 expected, observed/expected ratio (o/e) 1.08, 90% interval 0.94 to 1.24.
Homologues: Orthologues: chimpanzee HSD17B8 (100% identical), macaque HSD17B8 (96% identical), dog HSD17B8 (88% identical), guinea pig HSD17B8 (87% identical), mouse Hsd17b8 (87% identical), rabbit HSD17B8 (85% identical), rat Hsd17b8 (82% identical), pig HSD17B8 (72% identical), zebrafish hsd17b8 (59% identical), tropical clawed frog hsd17b8 (56% identical), Drosophila melanogaster CG3603 (49% identical). Paralogues in human: HSD17B10 (33% identical), HSD17B4 (32% identical), RDH11 (22% identical), SDR16C5 (22% identical), BDH1 (21% identical), HSD17B1 (21% identical), HSD17B2 (21% identical), HSD17B6 (21% identical), RDH5 (21% identical), HSD11B2 (21% identical), HSD17B13 (21% identical), HSD17B14 (21% identical), and 13 more.
Diseases named in the same sentence as HSD17B8 in open-access papers:
HSD17B8 is named in the same sentence as 18 diseases in open-access papers, as found by Europe PMC text mining. Sharing a sentence is not in itself a finding about the gene and the disease. The quoted sentences say what the papers report.
colorectal adenocarcinoma (2 papers, 2021 to 2024). The most common type of colorectal carcinoma. "GCAs generally exhibit different genetic mutations than colorectal adenocarcinoma; the HSD17B8 gene is upregulated in GCA, reflecting the endocrine nature of the tumour being involved in numerous endocrine cancers." (PMID 40729214, 2024). "Differential gene expression analysis showed distinct gene expression patterns in GCA compared to colorectal adenocarcinoma, with a number of cancer-related differentially expressed genes, including upregulation of TMEM14A, GOLT1A, DSCC1, and HSD17B8, and downregulation of KCNQ1OT1 and MXRA5." (PMID 34804955, 2021). "HSD17B8, a steroid dehydrogenase, plays a crucial role in the development of endocrine and endocrine-related cancers and was also found to be upregulated in GCA compared to colorectal adenocarcinoma, which may reflect the endocrine nature of GCA." (PMID 34804955, 2021).
autoimmune disease (1 paper, 2012). A disorder resulting from loss of function or tissue destruction of an organ or multiple organs, arising from humoral or cellular immune responses of the individual to their own tissue constituents. "Hydroxysteroid 17-beta dehydrogenase 8 (HSD17β8) is important in regulating the concentrations of active estrogens and androgens and high levels of estrogen are well known to be associated with SLE and other autoimmune diseases." (PMID 22928105, 2012).
chronic lymphocytic leukemia (1 paper, 2025). "For instance, HSD17B8 has colocalization with lymphoid leukemia and chronic lymphocytic leukemia; RPN1 has colocalization with myeloproliferative diseases (excluding CML) and polycythaemia vera; and PARP1 has colocalization with myeloproliferative diseases (excluding CML) and polycythaemia vera." (PMID 41048997, 2025).
liver fibrosis (1 paper, 2022). "In addition, we found that other CHB-related loci, such as HSD17b8, ITPR3, NUP205, RING1, and SKIV2l, were upregulated or downregulated in different ways in the groups with different degrees of liver fibrosis." (PMID 36406135, 2022).
cancer (3 papers, 2013 to 2021). A tumor composed of atypical neoplastic, often pleomorphic cells that invade other tissues. "Others have cancer-relevant functions, such as steroid hormone synthesis (HSD17B8, earlier), and covalent modification of histones (HUWE1, IPO7, MLL4, PAXIP1, PRKAA2, all later except PAXIP1)." (PMID 23762276, 2013).
tumor (3 papers, 2019 to 2024). "Among these genes, six (HOXA6, STC2, HSD17B8, TFAP2A, CYP1B1, and HOXC8) were reported to be osteogenesis-/chondrogenesis-related genes, and five (ADRA1A, TSPYL5, TES, TNFRSF10D, and MBP) were reported to be tumor-suppressor genes." (PMID 31889115, 2019).
HSD17B8 also shares sentences with these, for which no sentence is quoted: infection (3 papers); tuberculosis (3); alcoholic liver diseases (1); colon cancer (1); colorectal cancer (1); cystic fibrosis (1); endocrine cancers (1); lymphoid leukemia (1); malaria (1); myeloproliferative diseases (1); plague (1); polycythaemia vera (1).